INTS8 (integrator complex subunit 8)
Description:
Component of the integrator complex, a multiprotein complex that terminates RNA polymerase II (Pol II) transcription in the promoter-proximal region of genes. The integrator complex provides a quality checkpoint during transcription elongation by driving premature transcription termination of transcripts that are unfavorably configured for transcriptional elongation: the complex terminates transcription by (1) catalyzing dephosphorylation of the C-terminal domain (CTD) of Pol II subunit POLR2A/RPB1 and SUPT5H/SPT5, (2) degrading the exiting nascent RNA transcript via endonuclease activity and (3) promoting the release of Pol II from bound DNA. The integrator complex is also involved in terminating the synthesis of non-coding Pol II transcripts, such as enhancer RNAs (eRNAs), small nuclear RNAs (snRNAs), telomerase RNAs and long non-coding RNAs (lncRNAs). Within the integrator complex, INTS8 is required for the recruitment of protein phosphatase 2A (PP2A) to transcription pause-release checkpoint.
Synonyms: Int8; C8orf52; FLJ20530; MGC131633; NEDCHS
Tractability: PROTAC: ubiquitination databases record sites on it; its protein half-life has been measured.
Gene: Protein-coding gene on chromosome 8 (94,813,311 to 94,881,746, forward strand). Ensembl gene ENSG00000164941.
Subcellular location: Nucleus; Chromosome
Subcellular location (Human Protein Atlas): Nucleoplasm
Pathways (Reactome):
Gene expression (Transcription): RNA polymerase II transcribes snRNA genes
Gene Ontology:
Molecular function: protein binding
Biological process: protein localization to chromatin; regulation of transcription elongation by RNA polymerase II; RNA polymerase II transcription initiation surveillance; snRNA processing; snRNA 3'-end processing
Cellular component: chromatin; chromosome; INTAC complex; integrator complex; nucleus; nucleoplasm
Genetic constraint (gnomAD): Loss-of-function variants: 12 observed, 42.93 expected, observed/expected ratio (o/e) 0.28, 90% interval 0.18 to 0.45. The upper end of that interval is the gene's LOEUF score, 0.45, which puts it in group 2 of 6, group 1 being the genes least tolerant of losing a copy. Missense variants: 426 observed, 507.97 expected, observed/expected ratio (o/e) 0.84, 90% interval 0.77 to 0.91. Synonymous variants: 171 observed, 183.24 expected, observed/expected ratio (o/e) 0.93, 90% interval 0.82 to 1.06.
Homologues: Orthologues: chimpanzee INTS8 (99% identical), macaque INTS8 (99% identical), dog INTS8 (98% identical), rabbit INTS8 (98% identical), guinea pig INTS8 (97% identical), mouse Ints8 (96% identical), rat Ints8 (95% identical), pig INTS8 (89% identical), tropical clawed frog ints8 (77% identical), zebrafish ints8 (70% identical), Drosophila melanogaster IntS8 (28% identical), Caenorhabditis elegans ints-8 (19% identical).
Diseases named in the same sentence as INTS8 in open-access papers:
INTS8 is named in the same sentence as 33 diseases in open-access papers, as found by Europe PMC text mining. Sharing a sentence is not in itself a finding about the gene and the disease. The quoted sentences say what the papers report.
gastric cancer (4 papers, 2016 to 2024). A primary or metastatic malignant neoplasm involving the stomach. "In the last few years, both microarray and exome sequencing analyses have suggested a possible role of INTS8 in gastric cancer and peripheral T-cell lymphoma, respectively." (PMID 28468258, 2017). "The expression level of INTS8 in gastric cancer and paracancerous tissues suggests that it could be used as an early diagnostic molecule for gastric cancer." (PMID 38926181, 2024). "INTS8 (also known as C8orf52) has been identified as a potentially mutational driver gene in endometrial carcinoma; studies based on microarrays and exome-sequencing have proposed roles for INTS8 in gastric cancer and peripheral T-cell lymphoma." (PMID 30138346, 2018). "Interestingly, microarray- and exome sequencing-based studies proposed a role of INTS8 in gastric cancer and peripheral T-cell lymphoma." (PMID 28468258, 2017). "Limited studies indicate that INTS8 contains mutations in peripheral T cell lymphoma compared with non-malignant samples from 12 patients, and a combination of INTS8 with SULF1, ATP6V1C1, and GPR172A can be used to discriminate gastric carcinomas from adjacent noncancerous tissues." (PMID 27567667, 2016).
Intellectual disability (4 papers, 2017 to 2025). "Patients with mutations in INTS1 and INTS8 are affected by profound intellectual disability, borderline microcephaly, cerebellar hypoplasia and reduced volume of the pons and brainstem." (PMID 33686175, 2021). "We show here that mutations in the Integrator Complex Subunit 1 gene (INTS1) and Subunit 8 gene (INTS8) cause a severe neurodevelopmental syndrome, characterized by profound intellectual disability, epilepsy, spasticity, facial and limb dysmorphism and subtle structural brain abnormalities." (PMID 28542170, 2017). "Variants in INTS8 result in severe cognitive delay, speech absence, and motor impairment, whereas monoallelic variants in INTS6 lead to milder phenotypes, including speech–language problems, motor delays, and intellectual disability." (PMID 40966122, 2025). "The phenotype among the individuals with INTS8 and INTS1 mutations is similar, combining profound intellectual disability, epilepsy, lack of speech, facial and limb dysmorphism, altogether forming a recognizable syndrome." (PMID 28542170, 2017). "Biallelic pathogenic variants in INTS8 have been identified as the cause of neurodevelopmental disorder with cerebellar hypoplasia and spasticity (NEDCHS, OMIM #618572), characterized by severe developmental delay, significant intellectual disability, and absence of speech development." (PMID 41010026, 2025).
hepatocellular carcinoma (3 papers, 2021 to 2024). A malignant tumor that arises from hepatocytes. "A previous study revealed that INTS8 participates epithelial-to-mesenchymal transition in hepatocellular carcinoma (HCC)." (PMID 39027882, 2024). "Recently, a vivo study also demonstrated that integrator complex 8 (INTS8) promoted hepatocellular carcinoma proliferation and invasion through EMT marker (E‐cadherin) upregulation and activation of TGFβ/SMAD signaling pathway." (PMID 36284444, 2023).
endometrial carcinoma (2 papers, 2017 to 2018). A malignant tumor arising from the epithelium that lines the cavity of the uterine body. "In this regard, our pan-cancer investigation of mutations in the INT complex by OncodriveFML revealed that INTS7 and INTS8 can potentially be Mut-driver genes in endometrial carcinoma." (PMID 28468258, 2017).
metastatic tumors (2 papers, 2016 to 2024). "Moreover, high expression of INTS8 was associated with metastatic tumours and late stage, and with younger HCC patients (<65 years old)." (PMID 27567667, 2016). "Six genes were associated with tumour pathologic PT and tumour stage; among these, high expression of INTS8 and UBAP2L, and low expression of ACSM3, FCN2, LCAT, and MT1G, was significantly associated with metastatic tumour and late stage (P ≤ 0.05)." (PMID 27567667, 2016). "The results showed that the expression of INTS1, INTS7, and INTS8 transcripts in both HCC tumors and HCC metastatic tumors was significantly higher than that in normal tissues." (PMID 38926181, 2024). "Moreover, the expression of INTS1, INTS7, and INTS8 transcripts was significantly higher in both primary HCC tumors and HCC metastatic tumors compared to normal tissues, with the expression level in HCC metastatic tumors being significantly higher than in primary HCC tumors." (PMID 38926181, 2024).
brain malformations (1 paper, 2017). "In spite of sequencing INTS8 in 25 PNH patients and 266 other patients with brain malformations, we did not observe additional biallelic INTS8 mutations, which suggests that INTS8 mutational rate is very low." (PMID 28542170, 2017).
breast carcinoma (1 paper, 2017). "Additionally, INTS7 is specifically over-expressed in breast cancer, whereas INTS8 and INTS13 is particularly over-expressed in kidney renal clear cell carcinoma." (PMID 28468258, 2017).
colon cancers (1 paper, 2017). "However, statistically significant differences in the expression of INTS7, INTS8, and INTS13 between tumor and healthy samples were only measured for breast and colon cancers." (PMID 28468258, 2017).
congenital heart disease (1 paper, 2025). A heart disease that is present at birth. "Furthermore, the LOF variants identified in the low-LOUEF score genes FAM91A1, INTS8, and PDE2A have not been previously linked to congenital heart disease and are newly reported in this study." (PMID 40406060, 2025).
glioma (1 paper, 2021). A benign or malignant brain and spinal cord tumor that arises from glial cells (astrocytes, oligodendrocytes, ependymal cells). "Interestingly, a positive association between INTS8 and MMR genes was present in numerous cancers, such as brain lower-grade glioma, liver HCC, and pancreatic cancer." (PMID 34880328, 2021).
Joubert syndrome (1 paper, 2017). Joubert syndrome (JS) is characterized by congenital malformation of the brainstem and agenesis or hypoplasia of the cerebellar vermis leading to an abnormal respiratory pattern, nystagmus, hypotonia, ataxia, and delay in achieving motor milestones. "Also RPGRIP1L, mutated in Joubert syndrome with cerebellar hypoplasia, retinal dystrophy and variable cortical malformation, has disrupted alternative splicing in patients with INTS8 mutations." (PMID 28542170, 2017).
liver cancer (1 paper, 2024). An epithelial or non-epithelial malignant neoplasm that arises from the liver. "The expression of INTS1, INTS4, INTS7, and INTS8 increased with tumor progression, with all mentioned genes reflecting statistical differences in at least two groups of liver cancer tumor grades comparison." (PMID 38926181, 2024).
lung adenocarcinoma (1 paper, 2025). A carcinoma that arises from the lung and is characterized by the presence of malignant glandular epithelial cells. "Finally, by integrating the results of PPI network analysis and one-way COX regression analysis, we identified six RBPs that are both DEGs and associated with lung adenocarcinoma prognosis—IGF2BP3, SNRPE, GAPDH, MRPL12, MRPL15, and INTS8, with IGF2BP3 being the most differentially expressed." (PMID 40801655, 2025).
testicular germ cell tumours (1 paper, 2021). "Furthermore, a pan-cancer analysis of DNMTs was performed and showed that INTS8 was positively related to the expression profiles of 4 DNMTs in most cancers except testicular germ cell tumours." (PMID 34880328, 2021).
thyroid cancer (1 paper, 2017). "Although not significant, a mild reduction of INTS7, INTS8, and INTS13 expression was measured in thyroid cancer samples compared to normal ones." (PMID 28468258, 2017).
uterine corpus endometrial carcinoma (1 paper, 2017). A endometrial carcinoma (disease) that involves the body of uterus. "The INTS7 and INTS8 mutation patterns significantly differed from the background in uterine corpus endometrial carcinoma (UCEC) (INTS7, q-val = 0,182; INTS8, q-val = 0,184)." (PMID 28468258, 2017).
tumor (10 papers, 2016 to 2025). "We then examined the expression of proteins associated with INTS1, INTS3, INTS4, INTS7, and INTS8 in HCC through the Clinical Proteomic Tumor Analysis Consortium (CPTAC) and Human Protein Atlas (HPA) databases." (PMID 38926181, 2024). "The association between subtypes of tumour-infiltrating immune cells (TIICs) and INTS8 expression in CHOL was determined by using CIBERSORT tools." (PMID 34880328, 2021). "It was found that increased expression of INTS8 in the tumor tissue was associated with a more reduced overall survival and prognosis in patients with HCC." (PMID 33195699, 2020). "In addition, we found that INTS8 harboured the most prevalent mutations, such as missense, truncating and fusion mutations, in different tumours." (PMID 34880328, 2021). "In this study, we discovered that INTS1, INTS4, INTS7, and INTS8 exhibited high expression levels in tumor tissues compared to normal tissues in both the UALCAN and GEPIA2 systems (P < 0.05)." (PMID 38926181, 2024). "Our results showed that INTS8 overexpression was positively related to poor prognosis in many tumour types." (PMID 34880328, 2021). "Therefore, we analyzed the differential expression of INTS1, INTS3, INTS4, INTS7, and INTS8 in normal, further tumor, and metastatic HCC tissues using the TNM plotter." (PMID 38926181, 2024). "Subsequently, we investigated whether the expression levels of INTS1, INTS4, INTS7, and INTS8 correlated with patient tumor staging." (PMID 38926181, 2024). "Conversely, INTS7 and INTS8 exhibit oncogenic properties and may stimulate tumor growth, migration, and invasion." (PMID 37537630, 2023). "We found that stage (P = 0.050), tumour status (P = 0.001), DNASE1L3 expression (P = 0.042), and INTS8 expression (P = 0.023) were independent risk prognostic factors for OS in HCC patients, although no gene was found to be an independent prognostic factor for DFS (data not shown)." (PMID 27567667, 2016). "Our analysis indicated that INTS1, INTS4, INTS7, and INTS8 were highly expressed in HCC tissues, with their expressions closely correlated with tumor grade and poor prognosis of HCC patients." (PMID 38926181, 2024). "Seven-mutated genes detected from bcWES data are detected in single cells of either primary tumor or lymph node (fdr2d<0.2): MT-RNR2, MT-RNR1, MT-ND5, MT-TI, HUWE1, TMEM219 and INTS8." (PMID 31028395, 2019). "A transcriptome analysis of paired (normal and tumor) samples revealed that the transcription of INTS7, INTS8, and INTS13 is significantly altered in several cancers." (PMID 28468258, 2017). "The re-analysis of TCGA RNA-Seq data from paired samples (tumor vs. healthy) revealed a robust over-expression of INTS7, INTS8, and INTS13 genes in different tumors." (PMID 28468258, 2017). "Notably, INTS6 acts as a tumor suppressor by inhibiting the Wnt/β-catenin signaling pathway, thereby impeding HCC progression, whereas INTS8 enhances EMT via activation of the TGF-β pathway, promoting tumor aggressiveness." (PMID 41020855, 2025).
cancer (7 papers, 2015 to 2024). A tumor composed of atypical neoplastic, often pleomorphic cells that invade other tissues. "INTS8 encodes a subunit of the integrator complex that is involved in the cleavage of small nuclear RNAs, and its association with cancer is poorly understood." (PMID 27567667, 2016). "Furthermore, we observed that the co-expressed genes of INTS1, INTS4, INTS7, and INTS8 were involved in diverse processes associated with cancer development, underscoring their significant role in HCC progression." (PMID 38926181, 2024). "INTS2 and INTS8 are also miss-expressed or mutated in many cancers." (PMID 31311534, 2019). "Our study showed that high INTS8 expression is closely correlated with poor prognosis across cancers." (PMID 34880328, 2021). "Due to the extensive function of MMR genes in cancers, we performed a pan-cancer analysis to analyse the relationship between INTS8 and MMR genes." (PMID 34880328, 2021). "The expression levels of INTS8 in diverse cancer tissues, including the biliary tract, liver, and bone marrow, and cell lines were elevated to differing degrees." (PMID 34880328, 2021). "Therefore, INTS8 was identified as a therapeutic target in CHOL and pan-cancer series; an association was observed between INTS8 expression and TIICs; MMR genes and DNMTs were suggested to mediate INTS8 effects." (PMID 34880328, 2021). "However, to avoid bias caused by the small sample size, we used data from both the GEO and TCGA databases to confirm the findings, extended the potential functions and mechanisms of INTS8 to pan-cancer research, and discussed the functions of INTS8 in depth." (PMID 34880328, 2021). "Thus, we hypothesized that functional impairment of INTS8, which is associated with MMR genes and DNMTs, promotes malignancy across cancers, suggesting the potential of INTS8 for cancer research." (PMID 34880328, 2021). "Finally, the pan-cancer prognostic signature of INTS8 was identified by univariate analysis." (PMID 34880328, 2021). "Moreover, the pan-cancer analysis revealed that the altered expression of INTS8, which may be mediated by MMR genes and DNA methylation status, might participate in the development of multiple cancer types." (PMID 34880328, 2021). "We evaluated the correlations between INTS8 expression and mismatch repair (MMR) genes and DNA methyltransferases (DNMTs) in pan-cancer analysis." (PMID 34880328, 2021). "Our study highlights the significant role of INTS8 in CHOL and pan-cancers, providing a valuable molecular target for cancer research." (PMID 34880328, 2021). "Based on the diagnostic efficacy of the 5 mutant genes, we selected INTS8, which had the largest AUC value, for follow-up research, which showed that INTS8 played a significant role in CHOL and even across all cancers." (PMID 34880328, 2021). "In addition, the high INTS8 expression group presented significantly poor outcomes, including overall survival (OS), disease-specific survival (DSS) and disease-free interval (DFI) (p < 0.05) in pan-cancer." (PMID 34880328, 2021). "Despite the fact that we could not establish them as cancer drivers, INTS7 and INTS8 genes were highly mutated in specific cancers." (PMID 28468258, 2017). "Remarkably, despite not being able to definitely establish INTS7 and INTS8 as cancer driver genes, the transcriptome analysis of RNA-Seq paired samples revealed that these two genes, together with INTS13, are the most deregulated across cancers." (PMID 28468258, 2017).
neurological diseases (2 papers, 2021 to 2024). "Most interestingly, mutations in genes encoding the Integrator subunits INTS1 and INTS8 have been linked to a neurological disorder strikingly reminiscent of that affecting GAMOS patients with WDR73 mutations." (PMID 33686175, 2021). "More generally, we note that the Integrator complex is a known player in neurological diseases, with mutations in INTS1 and INTS8 being associated with rare recessive human neurodevelopmental syndromes." (PMID 39029934, 2024).
INTS8 also shares sentences with these, for which no sentence is quoted: peripheral T cell lymphoma (4 papers); cognitive delay (2); Cerebellar hypoplasia (1); ciliopathy (1); congenital cataracts (1); epilepsy (1); intrahepatic cholangiocarcinoma (1); kidney cancer (1); microcephaly (1); Neurodevelopmental delay (1); neurodevelopmental disorder (1); pancreatic cancer (1); renal carcinoma (1); Retinal dystrophy (1).